ESR1 (estrogen receptor 1)
Diseases named in the same sentence as ESR1 in open-access papers (continued):
Sharing a sentence is not in itself a finding about the gene and the disease.
breast cancer (continued). "Association of C6orf97/ESR1 SNPs with breast cancer in populations of different ancestries." (PMID 20661439, 2010). "Because the encoded enzymes and ESR1 are expressed in breast tissue, these SNPs may influence breast cancer risk by altering mammographic density." (PMID 19630952, 2009). "Because these enzymes and ESR1 are expressed in target tissues, these SNPs (or genetic factors with which they are in linkage disequilibrium) may alter breast cancer risk by altering mammographic density." (PMID 19630952, 2009). "In addition, results from this study suggest that women with BBD who carry the ESR2 *5772A>G polymorphism or the ESR1 – 104062C>T polymorphism are at decreased risk of developing breast cancer." (PMID 16808847, 2006). "The aim of this study was to simultaneously analyze ESR1 promoter methylation and ESR1 hotspot mutations in circulating tumor cells (CTCs) and paired plasma-circulating tumor DNA (ctDNA) from patients with estrogen receptor-positive (ER+) advanced breast cancer (BC)." (PMID 42201922, 2026). "ESR1 mutations are relatively prevalent in metastatic BC, with around 20–40% of patients treated with aromatase inhibitors (AI) exhibiting these mutations; such mutations are thought to account for resistance in 50% of metastatic breast cancer (mBC) patients." (PMID 40806432, 2025). "However, fulvestrant seems ineffective in patients with advanced breast cancer and ESR1 mutations." (PMID 38791941, 2024). "For instance, SCIN induced by the fusion of estrogen receptor 1 (ESR1) with PCDH11X (encoding a cell adhesion protein) or YAP1 (encoding a YES1-related transcriptional regulator) can induce epithelial-mesenchymal transition (EMT) of the breast cancer cell line T47D." (PMID 36874134, 2023). "Elacestrant has demonstrated antitumor activity in vitro and in vivo, including in an ER+HER2- breast cancer model against fulvestrant and cell cycle protein-dependent kinase 4/6 inhibitors as well as in resistance models with mutations in the estrogen receptor 1 gene (ESR1)." (PMID 38069380, 2023). "The research of ESR1 mutations in liquid biopsies based on the analysis of circulating cell-free DNA in plasma is of increasing interest and has been recently recommended to guide therapy in patients with estrogen receptor-positive breast cancers at progression under ET." (PMID 37958343, 2023). "Thus, exVARs considered were markers for short-term and long-term oxidative stress and levels of estrogens and activation of ESR1 in addition to breast cancer risk factors which were included to accounts for the action of breast cancer risk factors via mechanisms not reflected by the other exVARs." (PMID 34921608, 2022). "However, to account for possible other relations between breast cancer risk factors and activation of ESR1 (e.g., indirectly via activation of other signaling pathways) as well, breast cancer risk factors (BMI, smoking, intake of estrogen-active drugs) were additionally considered." (PMID 34921608, 2022). "Thus, the aim of the present study was to investigate the influence of intramammary estrogen levels and breast cancer risk factors on ESR1-dependent intercellular signaling and bioactivation of E2 and E1 to genotoxins and formation of adducts of estrogens with DNA." (PMID 34921608, 2022). "Additionally, it’s likely that some proportion of patients in this cohort harbored an ESR1 mutation - a known resistance mechanism of breast cancer to AI’s with a prevalence reported as high as 53% or greater in MBC24, though this was not assayed in this trial." (PMID 36369506, 2022). "New association studies with larger sample sizes and more comprehensive information about patients’ lifestyles are needed to clarify the association of ESR1 polymorphisms and synonymous mutations with breast cancer development to determine whether they are a relevant risk or prognostic factors." (PMID 33451133, 2021).
breast cancer (continued). "Recent studies have reported that the emergence of hormone therapy resistance in ER+ breast cancers can arise through four predominant mechanisms including ESR1 mutations (18%), altered MAPK signaling (13%), MYC or transcription factor activation (9%), and other/unknown factors (60%)." (PMID 33669749, 2021). "Furthermore, MAPK alterations were substantially enriched in patients with polyclonal ESR1 mutations as compared to single ESR1 mutations (39.3% versus 19.6% respectively, p = 0.0004), identifying a subset of oestrogen receptor (ER) positive breast cancers that develop polyclonal genomic resistance." (PMID 33893289, 2021). "Thus, ESR1 mutation detection is expected to become a prognostic and predictive biomarker in the near future, to be used in clinical practice for hormone-receptor positive (HR+) breast cancer, especially in the metastatic setting." (PMID 33535614, 2021). "Samples taken from newly diagnosed metastatic and loco-regional recurrence of endocrine-treated breast cancer showed that hotspot ESR1 mutations could emerge after or during adjuvant endocrine therapy including single-agent TAM, as well as during neoadjuvant endocrine treatment of primary tumors." (PMID 35201439, 2021). "Moreover, recombinant over-expression of a somatic mutation (Y537S) in the estrogen receptor (ER-alpha; ESR1), clinically associated with acquired Tamoxifen-resistance in breast cancer patients, genetically conferred elevated mitochondrial biogenesis, OXPHOS and high ATP production." (PMID 34722292, 2021). "ESR1 mutations may occur in breast cancer patients as above discussed." (PMID 32210163, 2020). "Furthermore, kinase fusions in breast cancer analyzed by Memorial Sloan Kettering-Integrated Mutation Profiling of Actionable Cancer Targets seemed to be enriched in hormone-resistant, metastatic carcinomas and mutually exclusive with ESR1 mutations." (PMID 33233830, 2020). "Research indicates that ESR1 mutations emerge during both metastatic breast cancer treatment and tumor evolution, and thus the need for a better-personalized treatment with aromatase inhibitor therapy that sequentially monitors and targets ESR1 mutations has been suggested." (PMID 32164570, 2020). "Furthermore, rapid and accurate detection of ESR1 alterations based on the advent of newly developed methods for differentiating subtypes and emerging variants resistant to currently used therapies will greatly benefit patients with advanced breast cancers." (PMID 33233830, 2020). "Therefore, as a gene encoding estrogen receptor, the genetic variation of ESR1, may expose the potential risk of breast cancer." (PMID 33149754, 2020). "On the basis of detection of ESR1 mutations in primary breast cancer using ctDNA analysis at a very low allele frequency, in contrast to a high allele frequency in metastases, it is plausible that in some tumors rare ESR1-mutant clones may be enriched by endocrine therapy." (PMID 32010431, 2020). "Interestingly, the authors found an enrichment of ESR1 amplifications in bone metastatic samples, suggesting that ESR1 amplification may underlie organ-specific metastatic behavior of ER+ breast cancers." (PMID 31106278, 2019). "Since increased proportion of dense breast tissue in adults represents a strong risk factor for breast cancer, the authors suggest that the methylation profile of ESR1 may modulate adolescent response to estrogen and may thus influence breast cancer risk in adulthood." (PMID 31261650, 2019). "High levels of ctDNA were significantly correlated with decreased overall survival (OS) in breast cancer (BC) and, more specifically, ESR1 cfDNA variants were associated with a shorter duration of endocrine treatment effectiveness in metastatic BC (MBC)." (PMID 30781720, 2019). "Thus, IRE1/XBP1 signaling is intimately linked to ESR1 signaling in luminal breast cancer." (PMID 30248920, 2018).
breast cancer (continued). "Together, the direct and indirect mechanisms of ESR1/ERα inhibition utilized by miR-22 suppress the oncogenic phenotypes associated with downstream ERα signaling activity, which makes miR-22 a promising candidate miRNA for therapeutic strategies to treat ER+ breast cancer." (PMID 30214383, 2018). "Likewise, in breast cancer patients mutations in the estrogen receptor (ESR1) have been hardly detected in primary tumors but are currently frequently reported in plasma from patients with metastatic disease that acquired resistance to aromatase inhibitor therapy." (PMID 27270325, 2016). "In addition, the rs3798758 A allele of ESR1 was associated with an increased risk of breast cancer (per-allele OR = 1.19, 95% CI: 1.04 to 1.37, P = 0.013), whereas the rs2228480 A allele of ESR1 was associated with a decreased risk (per-allele OR = 0.84, 95% CI: 0.72 to 0.98, P = 0.025)." (PMID 25116933, 2014). "Given that multiple independent breast cancer susceptibility loci have identified in our studies and studies conducted by others in 6q25.1 that harbors the ESR1 gene, it is possible that 6q25.1 may represent an important region for breast cancer susceptibility." (PMID 22383897, 2012). "In particular, miR-206 was reported to be associated with estrogen signals by targeting ESR1 (ERα) of breast carcinoma cell lines, and miR-221/222 could regulate estrogenic signals through ERα, resulting in the development of anti-estrogen resistant breast cancer." (PMID 23227519, 2012). "Although prior studies have not examined whether associations of CYP1A1 rs2606345 with mammographic density vary by BMI, a prior study reported that the association of an ESR1 SNP with increased breast cancer risk was apparent only among women with BMI greater than 25 kg/m2." (PMID 19630952, 2009). "These molecular evidence therefore highlight how Dex decreases the metastatic ability of ESR1 mutant breast cancer cells." (PMID 41261233, 2026). "ERαΔ7 occurred more frequently in luminal type breast cancer, with expression inversely correlating with ESR1 expression." (PMID 41703982, 2026). "Palazestrat showed potent antitumor activity in preclinical xenograft models of both ESR1 wild‐type and mutant human breast cancer." (PMID 41510186, 2026). "Differences in panel performance influenced association signals, including breast cancer candidate loci such as FGFR2, TOX3, and ESR1." (PMID 41871294, 2026). "In the Phase III VERITAC‐2 trial for advanced breast cancer, vepdegestrat significantly prolonged PFS in patients harboring ESR1 mutations compared with fulvestrant (5.0 vs." (PMID 41510186, 2026). "Here, we provide evidence that, in contrast to TNBC, activated GR in endocrine therapy-resistant ER+ breast cancer acts as an estrogen receptor silencer (ERS) that inhibits liver metastatic outgrowth by suppressing ESR1 expression." (PMID 41261233, 2026). "This evidence supports elacestrant monotherapy as an effective therapeutic option for appropriately selected patients with ESR1-mutant breast cancer, as reflected in real-world populations treated with this agent for advanced disease." (PMID 41201834, 2026). "Estrogen receptor (ER) mutations, particularly in the ESR1 gene, play a significant role in breast cancer development and treatment resistance." (PMID 40299687, 2025). "To confirm the clinical relevance of our findings, we analyzed LURAP1L-AS1 and ESR1, key regulator of mammary development, co-expression levels in a large breast cancer cohort (n = 1104) using the StarBase database." (PMID 39995981, 2025). "Studies suggest MDM2 is overexpressed in breast cancer cells positive for estrogen receptor 1 (ESR1/ER-alpha)." (PMID 40191734, 2025).
breast cancer (continued). "It is worth noting that, in current clinical practice, international guidelines recommend a rational use of NGS in advanced breast cancer, prioritizing targeted testing for known actionable mutations (e.g., PIK3CA, BRCA1/2, ESR1, etc.)." (PMID 41018107, 2025). "Among TNBC stage I-III (N = 321) and stage IV (N = 216) breast cancers, the most frequent alterations were mutations in PIK3CA (19.9% vs 21.3%), BRCA1/2 (11.5% vs 12.0%), ESR1 (0.31% vs 0%), PALB2 (0.9% vs 1.4%), and PD-L1 amplification (2.2% vs 4.6%)." (PMID 40421962, 2025). "Studies have found that SGK3 was transcriptionally activated by estrogen receptor ESR1 and high SGK3 expression was associated with poor prognosis of HR+ breast cancer patients." (PMID 40303291, 2025). "In the IRE1α–X-box binding protein 1 (XBP1) axis, knockdown of XBP1 has been shown to inhibit the growth of estrogen receptor 1 (ESR1)-positive breast cancer cells, demonstrating its pro-survival role in hormone-responsive tumors." (PMID 40564269, 2025). "In our model, SGK3 and ESR1 were markedly upregulated in alpelisib-resistant breast cancer cell lines." (PMID 40303291, 2025). "LMTK3, a key ERα regulator in breast cancer, stabilizes ERα via direct phosphorylation and promotes its transcription by inhibiting PKC, reducing AKT phosphorylation, and facilitating FOXO3 binding to the ESR1 promoter." (PMID 40641933, 2025). "N1ICD/RBPJ was showed to physically interact with ESR1 in breast cancer cells, forming a common complex bound to DNA, which enables ESR1-dependent activation of Notch1-mediated signaling." (PMID 40506655, 2025). "Estrogen receptor α (ESR–1) is a main biomarker and therapeutic target for endocrine therapy in breast cancer, and research on ESR–1 is mostly related to cancer." (PMID 40005889, 2025). "In luminal disease, structure-guided optimization has accelerated the development of next-generation oral SERDs, such as elacestrant and camizestrant, which have demonstrated clinical benefit in patients with ESR1-mutant advanced breast cancer." (PMID 41226779, 2025). "There was also a correlation between PARP2 and BRCA1/2 and ESR1 in the HER2 subgroup of breast cancer patients." (PMID 40141415, 2025). "Given this evidence, molecular characterization of the ESR1 gene through liquid biopsy is a promising approach for personalizing therapy in patients with advanced breast cancer." (PMID 41142848, 2025). "A recent study of patients with breast cancer reported that tumors with increased ZMIZ1 expression were correlated with decreased survival of ESR1-positive breast cancer patients." (PMID 41321316, 2025). "Liquid biopsy, which is collected through a blood draw, is used in patients with breast cancer to assess DNA mutations in genes such as PIK3CA and ESR1, which have FDA-approved targeted therapeutic interventions." (PMID 40427129, 2025). "ZMIZ1 is coexpressed with ESR1 in breast tumors and enhances the proliferation of breast cancer cells." (PMID 41321316, 2025). "Chromosomal abnormalities of the ESR1 gene identified in ET-resistant breast cancer include gene fusions within the same chromosome or with oncogenes on different chromosomes." (PMID 40244377, 2025). "Notably, the correlation between ex4:3 bp and both ESR1 mRNA expression and gene dependency scores ranked among the highest when compared with all other genes, emphasizing the strong association between ex4:3 bp expression and ESR1 gene function in breast cancer cells." (PMID 41258078, 2025). "In contrast, the results of studies in breast cancer cells suggest that PARP7 negatively regulates estrogen receptor α (ESR1) signaling." (PMID 40741921, 2025). "We show the sex-dependent role of E-cadherin in repressing ESR1 in human and mouse melanoma and breast cancer cells." (PMID 40500450, 2025).
breast cancer (continued). "For instance, the estrogen receptor (ESR1) is a well-known bimodally expressed gene in breast cancer patients, and Schlafen 11 (SLFN11), a bimodal predictive genomic biomarker, predicts response to DNA-targeted chemotherapy." (PMID 40647379, 2025). "In breast cancer patients, AATBC was analyzed alongside VDR- and ESR1-associated lncRNAs, showing correlations with histological grade." (PMID 40724881, 2025). "For example, in breast cancer, activation of Estrogen Receptor 1 (ESR1) broadly induces increased eRNA transcription, indicating the association between eRNAs and the activation of oncogenes or oncogenic signaling pathways." (PMID 41154834, 2025). "In HR+/HER2- breast cancer, 8.7% (87 of 995) of hotspot alterations associated with an on-label matched therapy were detected at a VAF <5%, comprising alterations in AKT1, ESR1, PIK3CA, and PTEN." (PMID 40711866, 2025). "It has been observed that mutations in the ESR1 and HER2 genes advance the development of breast cancer in females." (PMID 41323831, 2025). "Transcriptional regulation of ESR1 is crucial for mediating the downstream effects of estrogen signaling pathways, particularly cell growth in breast cancer." (PMID 40601671, 2025). "Meta‐analysis of retrospective data from breast cancer patients revealed that high levels of ESR1 indicate better prognosis throughout an 80‐month timeframe in Luminal A subtype, compared to low ESR1 expression." (PMID 39285617, 2025). "Taken together, enhanced stemness property and activated ESR1/SGK3/GSK3β/β-catenin pathway was discovered in the alpelisib-resistant breast cancer cells." (PMID 40303291, 2025). "These new SERDs, such as palazestrant (OP-1250), demonstrate superior performance in wild-type and ESR1-mutant breast cancer models compared to the existing treatments." (PMID 40299687, 2025). "Oestrogen receptor alpha (ER; gene symbol ESR1) is the most important prognostic and treatment‐predictive biomarker in breast cancer." (PMID 39108022, 2025). "The presence or absence of three receptors is particularly important when determining the type of breast cancer: the estrogen receptor (ESR1), the progesterone receptor (PGR), and the HER2 epidermal growth factor receptor (ERBB2)." (PMID 40143151, 2025). "An increase in KAT6A levels enhances ESR1 mRNA and ERα expression, which in turn is linked to more aggressive behaviors of ER+/HER2− breast cancer cells." (PMID 41357671, 2025). "Given the established role of Pbx1 as a pioneer factor for ESR1 in breast cancer cells and its necessity for E2 signaling, we conducted siRNA knockdown of Pbx1 to assess its involvement in E2-induced hernia pathogenesis." (PMID 39903526, 2025). "ESR1, whose protein defines the luminal subtype, is used for the clinical diagnosis of breast cancer, and is a target in hormone therapy." (PMID 40709098, 2025). "For instance, in luminal breast cancer, SERD development has benefited significantly from docking, VS, and MD simulations applied to ESR1 mutations." (PMID 41226779, 2025). "Other interesting observations included the mutual exclusivity of KEAP1 and STK11 in NSCLC and enrichment for CDH1, PIK3CA, and ARID1A along with mutual exclusivity with BRCA1/2, PTEN, and ESR1 in breast cancer." (PMID 40178042, 2025). "Selective ER degraders/downregulators (SERDs) have been developed to overcome endocrine resistance, particularly in ESR1-mutant breast cancers, which results in the constitutive activation of ER and reduced sensitivity to standard oestrogen therapies (ETs)." (PMID 41091336, 2025). "The only two entities with a larger proportion of ESR1 positive cases were breast cancer (15%), followed by endometrial carcinomas (7%)." (PMID 40282442, 2025). "Meanwhile, the elevated proportion of ESR1 positive cases in breast cancer cases, and to a lesser extent, in uterine cancer, show that these mutations are almost exclusively a consequence of ET." (PMID 40282442, 2025).